CASP8 (caspase 8)
Diseases named in the same sentence as CASP8 in open-access papers (continued):
Sharing a sentence is not in itself a finding about the gene and the disease.
cancer (continued). "Overall, these data highlight a role for Src-dependent Caspase-8 phosphorylation on Y380 in the mTORC1-dependent constitutive activation of NRF2 in cancer." (PMID 41053176, 2025). "Tumour cells with increased expression of gasdermin C (GSDMC) predicted better treatment response to PARPi in TNBC through the activation of GSDMC/caspase-8–mediated cancer cell pyroptosis (CCP) enhancing tumour microenvironment cytotoxicity." (PMID 40192976, 2025). "Pro-apoptotic caspases, such as caspase-3 and caspase-8, are enzymes that degrade cancer cell proteins when activated by apoptosis signals." (PMID 40362338, 2025). "Caspase 3/7 and Caspase-8 activities were increased from 0 min to 150 min in NaB treatment conditions in HCT-116 cancer cell lines." (PMID 40872562, 2025). "Caspase-8 expression is upregulated in many tumors where, despite its canonical apoptotic pathway, it sustains cancer progression promoting cell migration, NF-kB activation and inflammation." (PMID 41053176, 2025). "In contrast, IL-1RA and the FDA-approved drug Tolcapone both induce apoptosis by upregulating the expression of caspase-8 and caspase-3, resulting in cancer cell death." (PMID 40725140, 2025). "They worked by turning down a protein that helps cancer cells survive (Bcl2), boosting one that promotes cell death (caspase 8), and pushing more cancer cells into a stage where they die." (PMID 41283276, 2025). "Mechanistically, CD40L+CD8+ T cells can induce cell death in CD40-expressing cancer cells by triggering caspase-8 activation." (PMID 40397730, 2025). "Here, we provide the first evidence for a novel role of Caspase-8 in promoting the metabolic rewiring of cancer cells." (PMID 41053176, 2025). "While cancer cells with high levels of caspase-8 underwent apoptosis, caspase-8 depletion downregulated NF-κB signaling, increased RIPK1 stability, and facilitated necroptotic cell death." (PMID 38877579, 2024). "The involvement of caspase-8 in the expression of cytokines and chemokines has been observed in several cancer cells." (PMID 39625520, 2024). "Compounds 1, 6, 15, and 37 reduced the viability of cell lines via the intrinsic (caspase-9) and extrinsic (caspase-8) pathways of apoptosis, where 16 and 17 mainly influenced DNA biosynthesis in cancer cells." (PMID 38339241, 2024). "In contrast, in type II cells such as hepatocytes, pancreatic beta cells, and most cancer cells, the apoptotic signal requires amplification due to the low amount of caspase-8 generated at the DISC." (PMID 39513921, 2024). "Beyond this, CASP8’s status serves as a biomarker guiding therapeutic responses, enabling tailored treatment strategies for cancer with compromised CASP8 function." (PMID 39555097, 2024). "Quantification of caspase-8 activity after 24 h revealed that a short exposure to hypotonic medium significantly increased the sensitivity of cancer cells to exogenous sFasL." (PMID 38909035, 2024). "As a result, increased activation of caspase-9 and caspase-8 was recorded, together with stimulation of cancer cell apoptosis." (PMID 38339275, 2024). "Ginsenoside Rg3, for instance, can activate Caspase-8 via the extrinsic pathway, enhancing apoptosis in cancer cells." (PMID 39906672, 2024). "Growing evidence suggests that caspase-8 is instrumental in the occurrence and progression of cancer." (PMID 39440048, 2024). "Glabridin promotes tumor cell apoptosis by upregulating BAX, Caspase-3, Caspase-8, and Caspase-9 and downregulating Bcl-2, and inhibits cancer cell invasion and metastasis by downregulating N-Cadherin and upregulating E-Cadherin to reduce cell adhesion." (PMID 39723390, 2024).
cancer (continued). "TNFα promoted PANX1 cleavage via a caspase 8/3-dependent pathway to enhance cancer cell immunogenicity, leading to dendritic cell maturation and T-cell activation." (PMID 38195677, 2024). "Aberrant expression of PANoptosis-related genes (PRGs), such as NLRP3, caspase-8, and TNFAIP3, has been observed in various cancer types, with remarkable mutations detected." (PMID 38553639, 2024). "These divergences further underscore the importance of exploring the role of CASP8 across different cancer stages and subtypes." (PMID 39351539, 2024). "PARPi treatment triggered GSDMC/caspase-8–mediated cancer cell pyroptosis (CCP) that enhanced PARPi killing of tumor cells." (PMID 37883181, 2024). "Here, we will focus mainly on the role of Caspase-8 phosphorylation and on the acquired ability of cancer cells to redirect Caspase-8 to sustain tumor progression and resistance to therapy." (PMID 37444381, 2023). "In clinical samples, high Casp8 expression was related to better overall survival and cytotoxicity of T cells in cancer patients." (PMID 36635765, 2023). "This terpenoid significantly triggered apoptosis in the human colon cancer cell line, HCT116, by activating Caspase-8, -9, and -3 in these cancer cells." (PMID 37009004, 2023). "Here, we aim to review and discuss the role of Caspase-8 in cancer and its interplay with Src and other tyrosine kinases." (PMID 37444381, 2023). "For instance, in cancer, aberrant expression or malfunction of CASP8 can lead to tumor cells evading apoptosis, thereby affecting the development and spread of cancer." (PMID 38186679, 2023). "The CPNs simultaneously produce W-7 (a calmodulin antagonist) which promotes caspase-8 cleavage and increases cancer cell death." (PMID 37065863, 2023). "GSDME is cleaved by caspase-3 downstream of caspase-8 in cancer cells, intestinal epithelial cells, and macrophages." (PMID 37279255, 2023). "The heterogeneity in the genetic and epigenetic alterations of Caspase-8 in cancer, as well as in its function, represent crucial considerations in predicting the therapy response." (PMID 37444381, 2023). "Caspase-8 protein plays an important role in the development and progression of cancer, activating various structural and regulatory proteins involved in caspase-3 division." (PMID 37898675, 2023). "CASP8 mRNA levels were correlated with the cancer stages, patient weight, tumor histology and nodal metastasis status of ESCA patients." (PMID 36533709, 2023). "Studies have shown that KFSE can induce cancer cell apoptosis by regulating the protein expression of Bax and caspase 8, thereby inhibiting HepG2 cell growth." (PMID 37570647, 2023). "This widespread presence emphasizes the versatility of CASP8 in cellular processes, potentially affecting various aspects of cancer biology." (PMID 38186679, 2023). "An alternative mechanism to drive Caspase-8 downregulation in cancer relies on Caspase-8 promoter epigenetic silencing." (PMID 37444381, 2023). "When Bax proteins fail to target mitochondria and form aggregates, these tails are accessible for binding to the caspase 8 N-terminal death effector domain in cancer cells." (PMID 37371550, 2023). "Tumor necrosis factor-α (TNF-α) can trigger caspase 8-mediated apoptosis of cancer cells and the combination of IFN-γ and TNF-α can induce senescence of cancer cells." (PMID 38077389, 2023). "The activation of caspase 8 by FBF suggests a potential therapeutic strategy for cancers sensitive to death receptor-mediated apoptosis." (PMID 37570647, 2023).
cancer (continued). "The kinases responsible for carrying out Caspase-8 modifications are kinases typically known to be deregulated in cancer and many have already been extensively studied and used as targets of FDA-approved inhibitors." (PMID 37444381, 2023). "Caspase-8 is essential for PANoptosis, which can promote T cell-mediated immunity and inhibit tumor growth when it comes to cancer." (PMID 37666920, 2023). "Within most cancers, genes coding for pro-apoptotic caspases, such as CASP8, are often under genetic deletion pressures, leading to inactivation of apoptotic machinery." (PMID 37628814, 2023). "In vitro and in vivo evidence have recognized Caspase-8 in cancer as both an enhancer of cell motility and migration, a promoter of tumorigenesis and a sustainer of the increased inflammatory tumor microenvironment." (PMID 37444381, 2023). "Despite the increasing amount of data supporting a role for tyrosine phosphorylation in modulating Caspase-8 activity, little is still known about a clear crosstalk between cancer-related RTKs deregulation, Caspase-8 phosphorylation and its protumor role." (PMID 37444381, 2023). "This analysis focused on the functionally significant components of the multimeric RNAPII complex, including BRD4, HEXIM1, Spt5, NELF-A, Cyclin T, CDK9, LARP-7, and Caspase-8, which collectively serve as a regulatory hub in gene expression in cancer cells." (PMID 38201534, 2023). "Our research extended to a pan-cancer analysis, revealing CASP8's varied expression across different cancer types, and single-cell analysis techniques highlighted its extensive distribution across various cell types." (PMID 38186679, 2023). "EBV has been connected to various human cancers and immunity where nuclear receptor co-repressor 2 and caspase 8 play crucial roles." (PMID 37854612, 2023). "It inhibits the rapid growth, invasiveness, and metastasis of tumors by hindering the multiplication of cancer cells, and prompts apoptosis by avoiding cell division related to actuation of caspase-9 and caspase-8." (PMID 37259344, 2023). "Nar triggers an increase in the levels of caspase 3, caspase 8, Caspase 9, and BAX expression, all of which are associated with inducing apoptosis in cancer cells." (PMID 38004545, 2023). "This comprehensive examination indicated that CASP8 exhibits varied expression levels across multiple cancer types, highlighting its potential importance in the pathogenesis of a diverse range of cancers." (PMID 38186679, 2023). "The results of an interesting study indicate that PD-L1 mediates the atypical pyroptosis in cancer cells through GSDMC/caspase-8, leading to tumor necrosis." (PMID 37061535, 2023). "It prompts apoptosis by avoiding cancer cell division related to the actuation of caspase-9 and caspase-8 and permeabilization of the mitochondrial membrane, followed by the splitting of poly (ADP-ribose) polymerase-1." (PMID 37259344, 2023). "For other important cancer indicators, such as Caspase-8, Telomerase, Interleukine-6 and Interleukine-10, the Pa of all flavanones was lower." (PMID 37376079, 2023). "Delving further into the expression profile of CASP8, we extended our research to a pan-cancer analysis." (PMID 38186679, 2023). "The availability of genomic and transcriptomic data allowed reporting of significant variations in Caspase-8 expression in different cancer and these changes have been recently reviewed." (PMID 37444381, 2023). "In this way, we show that both statins and YAP/TAZ knockdown reduced the cellular levels of the caspase-8 inhibitor cFLIP and sensitized cancer cells to a TRAIL-induced and mitochondria-regulated apoptotic process." (PMID 37830584, 2023).
cancer (continued). "After exposing cancer cells to the tested compound, we observed 27.1% of the cell population with active caspase-8." (PMID 37047765, 2023). "PARP7 inhibition consequently destabilizes FRA1 and allows for the expression of inflammatory and proapoptotic genes, culminating in CASP8-mediated apoptosis of cancer cells." (PMID 38011562, 2023). "In this regard, we will focus on the role of Caspase-8 in cancer and we will discuss studies aimed at uncovering its multiple functions in cancer development and in the response to therapy." (PMID 37444381, 2023). "Specifically, we focus on the role played by tyrosine kinases in inhibiting the enzymatic role of Caspase-8 and remodulating Caspase-8 function in cancer through tyrosine phosphorylation." (PMID 37444381, 2023). "Based on specific cancer stages, when the expression of CASP8 was analyzed in ESCA we observed that the levels of expression in the four cancer stages were elevated when compared to healthy cells, with the maximum expression level occurring in stage 1." (PMID 36533709, 2023). "All crude extracts facilitated caspase-8 and -10 activation and induced apoptosis in cancer cells mediated by the activation of the endoplasmic reticulum (ER)-stress sensor binding protein (BiP)." (PMID 35879795, 2022). "Earlier, other carbazole alkaloids such as pyrayafoline-D, mahanine, and murrafoline-I also showed a similar kind of caspase-8-independent apoptosis in cancer cells." (PMID 35164236, 2022). "Pyroptosis-based cells exhibited the activation of caspase-8/3, the release of inflammatory factors (IL-18, IL-1β, etc.)and a strong relationship to inflammation, immunity and cancer." (PMID 36501209, 2022). "The four PRGs—CASP5, CASP8, IL6, and TIRAP—in this PPS were found to be closely associated with the development of cancers." (PMID 35255915, 2022). "The findings from the current study indicated that CLEFMA increased HO-1 production via the activation of p38 signalling and subsequently activated caspase-8, -9, and -3, which are critical for the anti-cancer action in HSC-3 and SCC-9 cells." (PMID 36428612, 2022). "Out of them, we selected 4 communities associated with genes CASP8, MAN2C1, BTN3A2 and ARL17A which are all reported in literature as possibly involved in cancer." (PMID 35061909, 2022). "TNFRSF10B has been shown to interact with FADD, caspase 10, and caspase 8 and induced apoptosis in cancer cells." (PMID 35399006, 2022). "In terms of cancer-related genes, POLQ and PREX2 in the regions of gains and CASP8 and SF3B1 in the regions of loss were found in all samples, including the tissue, plasma, and peritoneal fluid." (PMID 35626111, 2022). "The expression of GSDME varies in different cancers and is mainly activated by apoptotic caspase-3 and caspase-8." (PMID 35673561, 2022). "This GSDMC/caspase-8-mediated cell death provides new and valuable insights into the pathway of cancer cell pyrolysis." (PMID 35957895, 2022). "On the other hand, TNF-α derived from macrophages stimulates caspase-8 expression in cancer cells, which further specifically lyses GSDMC into N-GSDMC to induce pyroptosis." (PMID 35990696, 2022). "In brief, this study found a novel function of PD-L1 and identified that caspase-8/GSDMC mediates the pyroptosis pathway in cancer cells, which facilitates tumor necrosis." (PMID 35673561, 2022). "EME was shown to induce caspase-3, caspase-9/6, and caspase-8, followed by apoptosis induction in different human cancer cell lines." (PMID 36139404, 2022). "There is a body of literature demonstrating that the down-regulation of caspase-8 in cancer cells is accompanied with the methylation of its promoter region." (PMID 36112666, 2022). "UVC/SK2 stimulated more caspase 8 (+) counts, which were higher than caspase 9 (+) in cancer cells (Ca9-22 and OC-2)." (PMID 35625933, 2022). "In fact, it has been observed that caspase-8 and several other genes are known to be down-regulated in various cancers via DNA methyltransferase (DNMT) activity." (PMID 36112666, 2022).
cancer (continued). "Mdivi-1 is known to promote death receptor-mediated apoptosis through enhanced CASP8 activity in cancer cells." (PMID 34511600, 2022). "Since JNK reportedly promotes the expression of FasL, it is possible that JNK activates caspase-8 through the FasL/Fas death receptor pathway to induce cancer cell apoptosis." (PMID 38023774, 2022). "The presence of Caspase-8 in the earlier stages probably also assists the chemotherapeutic treatment of this cancer, eliciting a better prognosis." (PMID 36399280, 2022). "Although caspase 8 is considered to be mainly involved in the extrinsic pathway of apoptosis, its activation was also noted during apoptosis prompted by some anti-cancer agents e.g., cisplatin." (PMID 34769202, 2021). "Caspase-3, Caspase-8, Bax and Bcl-2 levels for hybrid 4b and staurosporine on HepG2 cancer cell line." (PMID 34832959, 2021). "We now know that gasdermin family members can also be cleaved by other proteases, such as caspase-3, caspase-8 and granzymes, and that they contribute to sterile inflammation as well as inflammation in autoinflammatory diseases or during cancer immunotherapy." (PMID 33868312, 2021). "In this context, we identified cytochrome C, apoptosis activation factor 1, and caspase 8, all of which were up-expressed in the HeLa cancer cells treated with P. plicata." (PMID 34961030, 2021). "Collectively, we concluded that GPx1 functions as the master regulator of the ASK1-JNK-cFLIP-caspase-8 axis in apoptosis pathways via stimulation-dependent interaction with TRAF2 in cancer cells." (PMID 34158609, 2021). "Caspase-8 has multiple roles in cancers by modulating both the expression profile of the tumor itself and the re-organization of the TME." (PMID 33026575, 2021). "The investigation of genetic and epigenetic alterations of caspase-8 in cancers provides better understanding of their impact on the therapy response." (PMID 33026575, 2021). "The fact that depending on the cancer type, caspase-8 is upregulated, downregulated, unaffected or post-translationally altered, suggests that its pro- and non-apoptotic functions are decided in a tumor entity-specific manner." (PMID 33026575, 2021). "These granules contain among others granzymes and perforin that trigger cancer cell lysis through formation of membrane lesions and induction of caspase-3 and caspase-8 activation." (PMID 34108958, 2021). "To validate the functions of Casp8 in the NK cells of cancer patients, we used flow cytometry to analyze PBMCs of patients with advanced cancer." (PMID 33934451, 2021). "Supporting this, SMAC mimetics combined with caspase-8 inhibitors have been shown to be effective in some cancer cell lines." (PMID 34025452, 2021). "Endoplasmic reticulum (ER) stress, as the common trigger of apoptosis, has been reported to induce CHOP-mediated DR5 transcription and CASP8-mediated extrinsic apoptosis in human cancer cells." (PMID 34195076, 2021). "Caspase-8 has been found to be involved in the expression of cytokines and chemokines in different cancer cells." (PMID 33026575, 2021). "Caspase-8 expression is often lost in some tumors, but increased in others, indicating a potential pro-survival function in cancer." (PMID 34482382, 2021). "The results showed that caspase-3 and caspase-8 in the extrinsic apoptotic pathway were activated in HSP-silenced cancer cells." (PMID 34557266, 2021). "More recently, our group has developed first-in-class small molecule inhibitors capable of disrupting FLIP recruitment to the DISC in cancer cells and inducing caspase-8 and FADD-dependent apoptosis." (PMID 34073507, 2021). "Both the absence and expression of caspase-8 were involved in tumor invasion and metastasis in cancers." (PMID 34482382, 2021). "The CD95 receptor can interact with CD95L (CD178/TNFSF6), which is expressed on T lymphocytes and NK cells to stimulate pro-apoptotic factors such as caspase-8 resulting in cancer cell apoptosis." (PMID 34641520, 2021).